OLR1 (oxidized low density lipoprotein receptor 1)
Diseases named in the same sentence as OLR1 in open-access papers (continued):
Sharing a sentence is not in itself a finding about the gene and the disease.
tumor (138 papers, 2011 to 2025). "The OLR1 gene, coding for an oxidized low-density lipoprotein receptor, is associated with tumor metastasis and apoptosis." (PMID 38942606, 2024). "Studies have linked OLR1 overexpression with increased cancer cell proliferation, invasion, and angiogenesis, emphasizing its significance in tumor progression." (PMID 39010054, 2024). "As for the OLR1 gene, a recent scRNA-seq analysis in head and neck tumors showed that OLR1 was specifically expressed on tumor-associated macrophages, and was significantly associated with worse overall survival of patients." (PMID 39001376, 2024). "OLR1 has been implicated in cardiovascular and metabolic disorders, while its association with tumorigenesis and tumor immunity remains poorly defined in the literature." (PMID 37629087, 2023). "There is evidence that the aberrant activation of OLR1 in PMN-MDSCs is associated with tumor immunosuppression." (PMID 37629087, 2023). "Together, the expression level of OLR1 in various cancers is closely associated with the infiltration of multiple immune cells and can be used as a marker of suppressive tumor immune response, and it is expected to serve as a predictor of ICI response." (PMID 37629087, 2023). "Our results suggest a potential association between OLR1 and pro-immunogenic tumor phenotypes; however, further mechanistic studies are required to elucidate the underlying molecular pathways, as well as clinical validations to determine its utility in guiding treatment decisions." (PMID 37629087, 2023). "Thus, we investigated the association between the metabolic gene OLR1 and tumor immunity in our study, aiming to ascertain its potential as a therapeutic target in cancer immunotherapy." (PMID 37629087, 2023). "Moreover, significant correlations are observed between OLR1 expression and tumor mutation burden (TMB) and microsatellite instability (MSI) in some cancers." (PMID 37629087, 2023). "Moreover, OLR1 (LOX‐1) is highly associated with G‐MDSCs at the tumour site, whereas G‐MDSCs has a unique gene expression profile compared with neutrophils." (PMID 35184420, 2022). "OLR1 can promote de novo lipogenesis and activate the NF‐kB signaling pathway to inhibit tumor cell apoptosis and promote cancer progression." (PMID 41176774, 2025). "In high-risk patients, APOD, OLR1, STC2, and DKK1 were found to be overexpressed, with APOD showing tumor-suppressive effects in certain cancers, while OLR1, STC2, and DKK1 are known to promote tumor growth and immune suppression." (PMID 39857718, 2025). "We observed that the levels of tumor-promoting cytokines were significantly increased in the mice inoculated with CAFs, but knocking down OLR1 attenuated this effect." (PMID 39010054, 2024). "MIHC analysis of GBC-LI sections also revealed OLR1 staining on oxLDL + neutrophils within the tumor area." (PMID 38822440, 2024). "We identified a novel state of tumor-infiltrated neutrophils distinguished by OLR1-mediated oxLDL uptake." (PMID 38822440, 2024). "The high expression of OLR1 in CAFs promotes the formation of metastatic nodules, increases tumor-promoting cytokine levels, and attracts more TAM infiltration." (PMID 39010054, 2024). "Overall, these findings indicate that GBC-neutrophil contact induces OLR1-mediated oxLDL uptake in neutrophils, leading to a pro-tumor phenotype." (PMID 38822440, 2024). "Overexpression of OLR1 is involved in enhancing the migration of tumor cells through NF-κB activation." (PMID 39684426, 2024). "Our study results revealed the potential significance of OLR1 in tumor immunity and prognosis; however, there are still some limitations worth considering." (PMID 37629087, 2023). "First, we observed a significant increase in OLR1 expression levels in tumor tissues compared to the normal controls in the TCGA-HNSCC dataset (p < 0.001)." (PMID 37629087, 2023).
tumor (continued). "Correlations between OLR1 expression level and tumor immunity and immunotherapy were investigated by immune infiltration, enrichment, and TIDE analysis methods." (PMID 37629087, 2023). "Despite these limitations, our study sets the stage for future research in this area and provides valuable insights into the potential role of OLR1 in tumor therapy." (PMID 37629087, 2023). "Considering the important role of OLR1 in driving tumor glycolysis and its relevance to the immunosuppressive tumor microenvironment and tumor metastasis, we further investigated the relationship between OLR1 and cuproptosis." (PMID 37629087, 2023). "Tumor growth rate and weight, and Ki67 expression were reduced in nude mice by sh-OLR1 treatment, which was negated by further oe-SULT2B1 treatment." (PMID 34921134, 2021). "We selected the 50 samples with the highest or lowest OLR1 expression levels from the 284 tumor samples and predicted the responder rate of the immune checkpoint blockade therapy in each group." (PMID 33959497, 2021). "Activated macrophage populations 2 and 3 were enriched in the tumor tissues and had lower expression of M1 phenotype signature compared to the OLR1+ macrophages." (PMID 33429363, 2021). "Given the limitation of the website, we chose 100 tumor samples (top 50 and bottom 50 samples of OLR1 expression in the last cohort) to run the TIDE prediction process." (PMID 33959497, 2021). "There were 16 kinds of TILs with different distribution between normal tissue and tumor tissue and 14 kinds of different distribution TILs between lower OLR1 expression tissue and higher OLR1 expression tissue." (PMID 33959497, 2021). "The T cell exclusion potential of the tumor was predicted to be negatively correlated with OLR1 expression." (PMID 33959497, 2021). "It has been reported that inhibition of OLR1 using siRNAsresulted in reduction of tumor growth in vivo and cancer cellmigration in vitro." (PMID 21637860, 2011). "Macrophage-associated OLR1 is significantly expressed in HNSCC and may be involved in the formation of an immunosuppressive tumour microenvironment." (PMID 38556542, 2024). "Additionally, SERPINA5 had differential expression in normal and metastatic tissues, while APP as well as OLR1 had differential expression in tumor and metastatic tissues (P < 0.05)." (PMID 39012409, 2024). "SPP1+ and OLR1 macrophages are suppressive immune cells that promote tumour progression." (PMID 39658531, 2024). "Notably, the proportion of neutrophils increased in the metastatic samples, transcriptionally resembling tumor-associated neutrophils (TAN), with a high expression of VEGFA, LGALS3, OLR1, PROK2, MMP9, and IL1RN." (PMID 38358826, 2024). "In contrast, a reduced expression of OLR1 was observed in tumor tissues of LUAD and LUSC." (PMID 37629087, 2023). "In addition, our in vivo experiments manifested that OLR1 silencing diminished tumor weight and volume, Ki67 expression, and tumor chemoresistance in nude mice." (PMID 34921134, 2021). "Of note, another research displayed that the inhibition of OLR1 could prevent the tumorigenesis and metastasis formation of CRC in xenograft tumors of nude mice, suggesting OLR1 as a promising target for suppression of tumor progression and metastasis of CRC." (PMID 34921134, 2021). "Moreover, t-SNE analysis showed a significant difference in the distribution of immune cells with 50% high or low OLR1 expression tumor samples." (PMID 33959497, 2021). "Furthermore, we found an interesting result when we compared TILs distribution between “normal vs. tumor” and “lower OLR1 expression vs. higher OLR1 expression”." (PMID 33959497, 2021). "It indicates that lower OLR1 expression has close relationship with tumor microenvironment." (PMID 33959497, 2021).
tumor (continued). "As indicated by western blot analysis, expression of LOX-1, c-MYC, and SULT2B1 in tumor tissues of nude mice was lowered by knocking down OLR1, whilst SULT2B1 expression in tumor tissues of nude mice was markedly strengthened by oe-SULT2B1 treatment in the presence of sh-OLR1As." (PMID 34921134, 2021). "In addition, xenografts experiments indicated that OLR1 accounted for many reported oncogenic activities, such as transformation of epithelial cells, proliferation, migration, tumor growth and apoptosis." (PMID 31718700, 2019). "OLR1 silencing effectively suppressed local tumor carcinogenesis of OS cells in vivo." (PMID 31718700, 2019). "This novel OLR1 procedure could account for much reported oncogenic activity, including transformation of epithelial cells, proliferation, migration, tumor growth and apoptosis." (PMID 26061746, 2015). "We also measured expressions of FABP5, GPNMB and OLR1 in the tumors and adjacent tissues, and found that they were expressed at significantly higher levels in the tumors than in the adjacent normal tissues, again confirming the ability of spheroids to mimic the in vivo tumor." (PMID 40176808, 2025). "Therefore, we preliminarily speculated that OLR1 might promote tumor development by recruiting these immunosuppressive cells to infiltrate the TME." (PMID 37629087, 2023). "In addition, several studies have shown that OLR1 may also be involved in the incidence and improvement of cancer, in particular tumour metastasis." (PMID 36452079, 2022). "Also, OLR1 silencing effectively suppressed local tumor carcinogenesis and lung metastases in vivo." (PMID 31718700, 2019). "The expression levels of ANGPTL4 and PPARD were notably higher in tumour tissue, whereas the expression levels of FABP1, SLC27A1 and OLR1 were elevated in normal tissue." (PMID 37556076, 2023). "Then, we used the tumor immune dysfunction and exclusion (TIDE) algorithm to evaluate the potential clinical efficacy of immunotherapy in different OLR1-expressing subgroups." (PMID 37629087, 2023). "In total, 72 genes were identified as significantly up-regulated, which include many genes (including OLR1, ICOS, and SERPINE1) that previous reports have demonstrated their correlation with tumor cell migration and metastasis." (PMID 37244923, 2023). "Intraperitoneal injection of rutin and SO alone for 14 days inhibited tumor growth, BANCR, and OLR1 levels, while promoted miRNA-590-5P expression." (PMID 34512168, 2021). "Many upregulated genes in the heat map have been reported to promote tumor metastasis, such as FOSB, OLR1, S100A9, MMP9, and ANGPTL4 36-40." (PMID 31598162, 2019). "The coordinated downregulation of KLF4, OLR1, CSF3, WIF1, RAMP3, and AGER, may impair tumor-suppressive mechanisms, thereby facilitating cancer progression, including enhanced tumor growth, migration, invasion, and metastasis." (PMID 40797277, 2025). "The process of the GBC-neutrophil contact and subsequent oxLDL uptake may involve much more sophisticated mechanism beyond tumor-expressed KRT17 and neutrophil OLR1 activation, which require future exploration." (PMID 38822440, 2024). "In addition, between tumor tissues and their paired adjacent normal tissues, ARHGAP25, SLAMF8 and OLR1 expression differed significantly." (PMID 38017548, 2023). "Correspondingly, due to the expression of Hsp receptors such as CD91 (α2-macroglobulin receptor or the low-density lipoprotein–related protein) and lectin-like oxidized low-density lipoprotein receptor-1 (LOX-1), HSP70 in APCs, the delivery of tumor antigen to APCs is improved through this approach." (PMID 35295845, 2022). "OLR1, STC2, and DKK1 correlate with tumor evolution and immunosuppressive effects." (PMID 34993138, 2021). "Interestingly, combined treatment with rutin and SO led to more significant inhibition of tumor volume, BANCR, and OLR1 levels, and promotion of miRNA-590-5P expression." (PMID 34512168, 2021).
tumor (continued). "First, phagocytosis of extracellular fatty acids via surface receptors including CD36, Olr1 (LOX1), and CD204 is a steady way in a fatty acid‐enriched environment, for instance, in a tumor microenvironment, explaining, that CD204 is suggested to be a marker of tumor‐infiltrated macrophages." (PMID 31602788, 2019). "The OLR1 expression level was related to cell migratory potential in vitro, and its downregulation could inhibit EMT and tumor metastases in vivo." (PMID 31718700, 2019). "In addition, OLR1 may be involved in reprogramming the lipid metabolism of tumour cells in HNSCC, thereby altering the tumour immune microenvironment and affecting the prognosis of patients." (PMID 38556542, 2024). "However, the precise role of OLR1 in different tumor types, including HNSCC, and its relevance to tumor immunity and immunotherapy remain unclear in the research." (PMID 37629087, 2023). "Similarly, the oxidized low-density lipoprotein receptor 1 (OLR1) gene, which plays an important role in the humoral immunity of the skin, and the plexin D1 (PLXND1) gene, which is highly expressed in tumor vasculature, were both found to be common targets of miR-27b, miR-1914, and miR-612." (PMID 31766385, 2019). "Considering the complexity of PDAC architecture, the true “invasive front” of a tumor cannot be reliably identified in a 2-dimensional tissue section, so we could not determine whether SPOCK1 or OLR1 expression was enhanced in the most invasive PDAC cells in vivo." (PMID 36881486, 2023).
cancer (117 papers, 2011 to 2026). A tumor composed of atypical neoplastic, often pleomorphic cells that invade other tissues. "In conclusion, we observed that OLR1 was abnormally upregulated in pan-cancer and was associated with prognostic outcomes." (PMID 37629087, 2023). "Lectin-like oxidized low-density lipoprotein receptor-1 (LOX-1), a translated protein of OLR1, has also been implicated in cancer." (PMID 37629087, 2023). "Proteins SOX5, SON, and OLR1 have been implicated in various aspects of cancer progression and metastasis." (PMID 38003292, 2023). "OLR1 had been implicated in the tumorigenesis or progression of several types of cancers by a series of studies." (PMID 31718700, 2019). "OLR1 is highly expressed in most cancers, and it is associated with patient prognosis." (PMID 37629087, 2023). "Therefore, as a follow-up to our pan-cancer analysis, we further investigated the underlying mechanisms by which OLR1 influences HNSCC progression, the sixth most common cancer worldwide." (PMID 37629087, 2023). "Studies also suggested multiple potential associations between OLR1 and cancer susceptibility, such as OLR1 over-expression in human cancer cell line associated with obvious upregulation of several oncogenes and significant increase in cell apoptosis, proliferation and migration." (PMID 26061746, 2015). "The observed involvement of OLR1 in cancer establishment and progression and the active role of alternative splicing in the generation of splice variants with different effects on disease, implicates a critical role for OLR1 splice variants in cancer that is yet to be fully understood." (PMID 28146073, 2017). "High expression of oxidized low-density lipoprotein receptor 1 (OLR1) is associated with recruitment of immune cells such as macrophages and cancer-associated fibroblasts." (PMID 40486875, 2025). "Research has demonstrated that overexpression or ectopic expression of OLR1 can stimulate cancer cell proliferation and expedite the onset, progression, and metastasis of cancer." (PMID 39012409, 2024). "Our identification of OLR1 as significantly overexpressed in CAFs expands on existing knowledge regarding fibroblast-specific markers in cancer contexts." (PMID 39010054, 2024). "To this end, we investigated the correlations between OLR1 and 17 common immune checkpoint expressions in pan-cancer." (PMID 37629087, 2023). "Collectively, our results suggest that OLR1 expression levels are significantly elevated in the progression of various cancers and have the potential to serve as a prospective pan-cancer prognostic biomarker, particularly for COAD, HNSCC, LGG, and CHOL." (PMID 37629087, 2023). "The effects of OLR1 have been studied in metabolic and cardiovascular diseases; however, it is also overexpressed in some cancers and involved in various tumorigenic processes." (PMID 37629087, 2023). "In this study, we used multiple public databases to evaluate OLR1 expression and its relationship with prognosis in 33 cancer types, and to explore correlations between OLR1 expression levels and immune infiltration and immune checkpoint expression." (PMID 37629087, 2023). "The results show that OLR1 is markedly upregulated in the majority of cancers, with a few exceptions." (PMID 37629087, 2023). "We conducted comprehensive pan-cancer analyses based on the TCGA database to examine OLR1 expression and its prognostic implications." (PMID 37629087, 2023). "To investigate the prognostic significance of OLR1 expression across 33 different types of cancer, we performed a survival analysis using a Cox proportional hazards model." (PMID 37629087, 2023). "Ox-LDL binds to the lectin-like oxidized low-density lipoprotein receptor-1 (LOX-1) and cluster of differentiation 36 (CD36) to induce mutations, resulting in inflammation, cell proliferation, and metastasis of cancer." (PMID 35251975, 2022).